EZH2 (enhancer of zeste 2 polycomb repressive complex 2 subunit)
Diseases named in the same sentence as EZH2 in open-access papers (continued):
Sharing a sentence is not in itself a finding about the gene and the disease.
B-cell lymphomas (128 papers, 2011 to 2026). "A recent study in PLoS Biology used simultaneous measurements of histone modifications in single cells to reveal that EZH2 gain-of-function mutations profoundly reprogram chromatin states in B-cell lymphoma, while also increasing their cell–cell heterogeneity." (PMID 40512686, 2025). "This concurrently rules out the possibility of paradoxical hypermorphic activity, which is known to occur with certain somatic EZH2 variants found in B cell lymphomas." (PMID 38015625, 2024). "EZH2 is highly expressed in germinal center (GC) B cells and targeted by somatic mutations in B cell lymphomas." (PMID 35773729, 2022). "EZH2 mutations, especially hotspot mutations affecting Y641, drive B cell lymphoma development, and EZH2 inhibition is considered an attractive therapeutic option in EZH2-mutated B cell lymphomas, including DLBCL." (PMID 35380993, 2022). "In fact, the mutation at the Y641 amino acid in the EZH2 gene is mutated in up to 40% of B-cell lymphomas." (PMID 36230571, 2022). "B cell lymphomas often have activating mutations in EZH2, and some subtypes of sarcomas have mutations in SWI-SNF subunits SMARCB1 (BAF47) or SMARCA4 (BRG1)." (PMID 35852858, 2022). "Accordingly, loss-of-function mutations in KMT2D can occur in B-cell lymphomas together with GOF mutations of the EZH2 gene." (PMID 34202528, 2021). "EZH2 gain-of-function mutations are among the most common genetic alterations identified in GC-derived B-cell lymphoma." (PMID 34857028, 2021). "Recently, several EZH2 inhibitors have exhibited promising therapeutic effects in GC-derived B-cell lymphoma patients bearing EZH2-activating mutations." (PMID 34503063, 2021). "Mutated EZH2 in B-cell lymphoma enables persistent epigenetic silencing of genes involved in PC differentiation and negative regulation of cell cycle." (PMID 34857028, 2021). "EZH2 is important in the formation of GC in mice and it has been shown that mutations in EZH2 in addition to overexpression of BCL2 lead to B cell lymphomas." (PMID 34193230, 2021). "In B-cell lymphomas the heterozygous point mutations affecting EZH2 at Y641 are in the catalytic domain." (PMID 34857028, 2021). "In this study, we demonstrated that the combination of EZH2 inhibitor SHR2554 and HDAC inhibitor HBI8000 exert synergistic anti-proliferative activity in both EZH2 wide-type and mutation B-cell lymphoma." (PMID 34503063, 2021). "In this study, we aimed to investigate the molecular mechanism underlying acquired resistance to DZNep in B-cell lymphoma, and to identify biomarkers predictive of the therapeutic success of EZH2 inhibition with DZNep." (PMID 32408898, 2020). "Treatment with EZH2 inhibitors is being investigated in follicular and B-cell lymphomas with activating EZH2 mutations, and in solid tumors with overexpression of EZH2, which are associated with a poorly differentiated phenotype." (PMID 33339101, 2020). "The mutation of EZH2 in B-cell lymphomas motivated the development of small-molecule inhibitors that act as SAM-competitive binders of the SET domain and exhibit high selectivity for EZH1/2." (PMID 31123059, 2019). "A complicating factor is the identification of secondary mutations in both wild-type and mutant EZH2 alleles in B-Cell lymphoma cells lines, which can cooperate to confer resistance to EZH2 inhibitors." (PMID 31123059, 2019). "The histone methyltransferase inhibitor tazemetostat, an EZH2 inhibitor, is tested for relapsed or refractory B cell NHL with EZH2 mutations." (PMID 31405121, 2019). "For example, selective inhibitors, such as EPZ005687, GSK126, and EI1, which target EZH2 of PRC2, were recently reported by three independent groups to inhibit proliferation of B-cell lymphomas harboring EZH2-activating mutations." (PMID 28665350, 2017). "Two other clinical trials (NCT02395601 and NCT02082977) of SMARCB1-deficient tumors and EZH2-mutant B cell NHL are underway." (PMID 28415635, 2017).
B-cell lymphomas (continued). "EZH2 inhibitors seem to be particularly effective against B cell lymphomas bearing EZH2-activating mutations." (PMID 27222667, 2016). "To identify mechanisms of acquired EZH2i resistance, we used the B-cell lymphoma Pfeiffer cell line as a model system, since it naturally harbors an EZH2 A677G mutation that renders it highly sensitive to EZH2i." (PMID 26360609, 2015). "Together, these findings suggest that EZH2 inhibitors such as GSK126 are potential novel epigenetic intervention reagents for B-cell lymphoma harboring gain-of-function EZH2 mutations." (PMID 23494175, 2013). "Significantly, EZH2 inhibitor GSK126 eradicated the growth of xenografted B-cell lymphoma cells with EZH2 mutations." (PMID 23494175, 2013). "For example, translocations involved the H3K36 methyltransferase Nsd1 are linked to leukemias, whereas activating point mutations in the H3K27 methyltransferase Ezh2 are linked to B cell lymphoma." (PMID 23520493, 2013). "Our findings confirm and extend prior work regarding the prevalence of EZH2 mutations in B cell lymphomas and the molecular function of these mutations." (PMID 22194861, 2011). "Epigenetic regulators such as EZH2 are known to be mutated in B cell lymphomas, but the effect of these mutations remains unclear." (PMID 40504770, 2025). "This Primer discusses a recent study using simultaneous measurements of histone modifications in single cells to reveal that EZH2 gain-of-function mutations profoundly reprogram chromatin states in B-cell lymphoma, while also increasing their cell-cell heterogeneity." (PMID 40512686, 2025). "EZH2 is highly expressed in GC B cells and targeted by somatic mutations in B-cell lymphomas." (PMID 35463343, 2022). "In hematological malignancies, loss of function mutations of EZH2 are reported in T-cell acute lymphocytic leukemia, myelodysplastic syndromes, and myeloproliferative neoplasms, however, gain of function mutations are observed in B-cell lymphomas." (PMID 34857028, 2021). "In addition, the mutation of EZH2 alanine 677 to glycine (A677G) in B-cell lymphoma cell lines and primary tumor specimens resulted in aberrantly elevated H3K27me3." (PMID 33761979, 2021). "The combination of EZH2 inhibitor and HDAC inhibitor could provide a potential therapeutic treatment for both EZH2 wide-type and mutation B-cell lymphoma patients." (PMID 34503063, 2021). "Moreover, a phase II study of tazemetostat in patients with relapsed or refractory B-cell NHL harboring EZH2 mutations is ongoing (NCT03456726)." (PMID 33761979, 2021). "Furthermore, EZH2 has been linked to decreased CD58 expression in B-cell lymphoma, with high H3K27me3 levels at the CD58 promotor region, and increased CD58 expression upon EZH2 inhibition." (PMID 33260693, 2020). "Dozens of chemotherapeutic agents have been developed to target the EZH2 enzymatic SET domain for therapeutics; yet, for most of these drugs, satisfactory effectiveness was only seen in B cell lymphoma cell lines or xenografts with EZH2 gain-of-function mutations." (PMID 31752930, 2019). "A better understanding of the EZH2 target genes allowed the authors to associate Tazemetostat with B-cell pathway inhibitors to increase the specificity and the efficacy of this treatment in B-cell lymphoma with wild-type EZH2." (PMID 34991274, 2018). "EZH2 pathologic activation due to gain-of-function mutations and the associated increase in H3K27me3 at target genes have been clearly demonstrated to be essential for the development of germinal center derived B-cell lymphomas." (PMID 26755663, 2016). "Although EZH2 mutation alone may be insufficient to induce development of B-cell lymphoma, new evidence suggests it functions as a master regulator of GCB phenotype through repression of CDKN1A, IRF4, and PRDM1." (PMID 24622842, 2014).
B-cell lymphomas (continued). "BACKGROUND: Numerous genomic abnormalities in B-cell non-Hodgkin lymphomas (NHLs) have been revealed by novel high-throughput technologies, including recurrent mutations in EZH2 (enhancer of zeste homolog 2) and CD79B (B cell antigen receptor complex-associated protein beta chain) genes." (PMID 23361872, 2013). "In this study, we report the results of testing for EZH2 codon 641 mutations in a large series of B cell lymphomas of germinal center origin, using a sensitive and specific single nucleotide extension method (SNaPshot) which has been validated for clinical tumor genotyping at our institution." (PMID 22194861, 2011). "These inhibitors could suppress H3K27 tri-methylation, reactivate silenced PRC2 target genes and demonstrated effectiveness in inhibition of cell survival in GC-derived B cell lymphomas harboring EZH2-activating mutations amid several types of lymphoid malignancies." (PMID 31752930, 2019). "Moreover, as EZH2 and DNMTs cooperate in transcriptional regulation, it might be interesting to explore the effects of associating EZH2 inhibitors with DNA demethylating agents in B-cell lymphoma cells." (PMID 26497210, 2016). "SAM-competitive EZH1 and EZH2 dual inhibitors have been approved by the FDA for treating B-cell lymphoma and other cancers." (PMID 42314051, 2026). "The purpose of this article is to review the role of EZH2 in normal B cell differentiation and in the pathogenesis of B-Cell lymphomas." (PMID 42211521, 2026). "In B-cell lymphoma, EZH2 inhibition can increase the expression of the chemokine C–C motif chemokine ligand 17, induce T-cell chemotaxis, and promote the T-cell-rich tumor microenvironment." (PMID 40028035, 2025). "Compared with solid tumors and B-cell lymphomas, targeting EZH2 in T-cell lymphomas is still in the early stages of investigation." (PMID 38339397, 2024). "An open-labeled multicentric arm phase-1 study identifying EZH2 inhibitor (XNW5004) efficacy in R/R B cell lymphoma, including MCL." (PMID 37626420, 2023). "At present, targeted therapies for EZH2 are mostly focused on the hematologic and lymphatic systems, such as B-cell lymphoma and non-Hodgkin’s lymphoma." (PMID 36672374, 2023). "Myc acts as a repressor of miRNA-29 by recruiting histone deacetylase 3 (HDAC3) and EZH2 in aggressive B-Cell lymphomas." (PMID 35892859, 2022). "Tazemetostat shows promising activity in aggressive B-cell lymphoma, such as r/r GCB-type DLBCL, especially when EZH2 is mutated." (PMID 35794096, 2022). "In B cell lymphomas, EZH2 is highly expressed and is required to maintain germinal center formation and prevent plasma cell differentiation." (PMID 35426374, 2022). "While EZH2 inhibitors are already being evaluated in phase 1 and 2 clinical trials in different solid tumors and B cell lymphoma, not only in MDS but also in AML, EZH2 is increasingly under study as a potential therapeutic target." (PMID 33845873, 2021). "CPI-1205, the third selective EZH2 inhibitor, was orally administered twice a day in 32 patients with B-cell lymphomas." (PMID 33868269, 2021). "It has been demonstrated that several EZH2-target agents have notable therapeutic effects in EZH2-mutant B-cell lymphoma patients." (PMID 34503063, 2021). "GSK2816126, a highly selective inhibitor of EZH2, was applied for the treatment of 41 patients with solid tumors or B cell lymphoma." (PMID 33868269, 2021). "PRC2-independent EZH2-mediated transcriptional activation was previously reported in prostate cancer and B-cell lymphoma through collaboration with transcriptional activators like E2F1." (PMID 34857028, 2021). "EZH2 is highly expressed in many tumors, and its inhibitor Tazemetostat has shown good safety and antitumor activity in refractory B-cell non-Hodgkin’s lymphoma and advanced solid tumors (including epithelioid sarcoma)." (PMID 34001062, 2021). "The EZH2-targeted drugs have demonstrated notable therapeutic effects in EZH2 mutant B-cell lymphoma patients." (PMID 34503063, 2021).
B-cell lymphomas (continued). "Tazemetostat is a drug known to inhibit EZH2 and has been shown to reduce growth in medulloblastoma, B-cell non-Hodgkin lymphoma and epithelioid sarcoma." (PMID 33316946, 2020). "EPZ011989, another selective and orally bioavailable EZH2 inhibitor reported in 2015, was able to inhibit tumor growth significantly in a mouse xenograft model of human B cell lymphoma." (PMID 32723346, 2020). "In B cell lymphoma, heterozygous point mutation occurred at the tyrosine 641 within the C-terminal catalytic SET domain of EZH2." (PMID 32723346, 2020). "EZH2 was recently confirmed to be a therapeutic target, as the EZH2 inhibitor Tazemetrostat showed antitumor activity against refractory B-cell lymphoma and advanced solid tumors in phase I clinical trials." (PMID 31042721, 2019). "Dual-targeting of MYC and EZH2 has been employed to disrupt MYC-EZH2 oncogenic axis in aggressive B cell lymphoma cells." (PMID 31752930, 2019). "In B cell lymphomas, overexpressed EZH2 hypermethylates the promoter of FAS-AS1 lncRNA and represses the FAS-AS1 expression, leading to impaired FAS-mediated apoptosis." (PMID 31752930, 2019). "In particular, JAK2 phosphorylation of EZH2 at tyrosine 641 is able to promote EZH2 degradation via the SCFβ-TrCP E3 ubiquitin ligase pathway in B cell lymphoma." (PMID 30159126, 2018). "Heterozygous point mutations affecting tyrosine 641 (Y641) within the C-terminal catalytic SET domain of EZH2 have been identified in B-cell lymphomas [diffuse large B-cell lymphoma (DLBCL) 22%; follicular lymphoma 7–12%]." (PMID 29556394, 2018). "A multicenter, open-label, Phase 2 study (NCT03456726) to assess the efficacy and safety of tazemetostat, an EZH2 inhibitor, in participants with relapsed or refractory B-cell non-Hodgkin’s lymphoma is currently ongoing." (PMID 30486864, 2018). "GSK126, an EZH2 inhibitor, markedly suppresses the growth of several types of cancer, including B-cell lymphoma." (PMID 28418882, 2017). "EZH2-specific inhibitors have recently been developed, and their anti-tumor activity has been demonstrated in various cancer types, including B-cell lymphoma." (PMID 28418882, 2017). "Additional findings to support an oncogenic role for EZH2 have recently emerged; recurrent mutations of the tyrosine 641 (Y641) and alanine 677 (A677) residues of EZH2 have been reported in B-cell lymphomas." (PMID 28418882, 2017). "Last year, the development of EPZ011989, a selective and orally available EZH2 inhibitor, was reported and was shown to have significant activity in a mouse xenograft model of B cell lymphoma." (PMID 27793053, 2016). "Recently, EZH2 has become a high priority therapeutic target in multiple cancers, including aggressive B-cell lymphomas." (PMID 26973857, 2016). "For instance, recent in vitro studies have highlighted the synergy between EZH2 inhibitors and HDACi in aggressive B-cell lymphoma." (PMID 26497210, 2016). "Ultimately, these results provide exciting potential for the combination of genotoxic therapy with inhibitors of EZH2 as a novel therapeutic strategy for patients with aggressive treatment resistant B-cell lymphomas." (PMID 26973857, 2016). "In March 2015, they have begun a phase I clinical trial of CPI-1205, a novel inhibitor of EZH2, in patients with B cell lymphomas (ClinicalTrials.gov identifier: NCT02395601)." (PMID 27222667, 2016). "Overall, we demonstrate that inhibition of histone methyltranferase EZH2 regulates cell fate decisions in response to genotoxic chemotherapy in multi-drug resistant models of B-cell lymphoma." (PMID 26973857, 2016).
B-cell lymphomas (continued). "In aggressive B-cell lymphomas, c-MYC-mediated recruitment of EZH2 causes H3K27me3-dependent silencing of the tumor suppressor miR-26a, and c-MYC or EZH2 inhibitors reactivate miR-26a expression in this malignancy." (PMID 25968566, 2015). "This study sought to determine the evolution of the mutational status of EZH2 and CD79B over time in different samples from the same patient in a cohort of B-cell NHLs, through use of a customized multiplex mutation assay." (PMID 23361872, 2013). "We concluded that similarly to CIITA, EZH2, and CREBBP mutations, IRF8 variants may add to the pathogenesis of B cell lymphomas by impairing antigen presentation in the context of MHCII." (PMID 38996030, 2024). "More recently, we and other groups found EZH2 overexpression in a range of hematologic malignancies including B-cell lymphomas, Hodgkin lymphomas, histiocytic and dendritic cell neoplasms, subsets of T-cell neoplasms, plasma cell neoplasms, and myeloid neoplasms." (PMID 38339397, 2024). "Furthermore, two cell lines from the B-cell lymphoma background with high interest in EZH2 inhibition were used for comparison as they either carry an activating EZH2 mutation or show high EZH2 expression, respectively." (PMID 37297005, 2023). "Interestingly, both EZH1 and EZH2 are functional not only in multiple lymphomas with wild-type EZH2 but also in certain B-cell lymphomas with heterozygous mutant EZH2, and the dual inhibitor is more effective." (PMID 36239901, 2022). "In addition, activating mutations at Y641 amino acid in the EZH2 gene within the EZH2 catalytic SET domain are recurrently and significantly mutated in up to 40% of B-cell lymphomas, and particularly in approximately 13–22% of DLBCL." (PMID 36230571, 2022). "Interestingly, the latest subclassification of DLBCL contains a cluster of human B-cell lymphomas, driven by deregulated methyl transferases, such as EZH2 or MLL4, that often occur together with MYC and BCL-2 alterations." (PMID 36611833, 2022). "Thus, Ezh2 inhibitors are being trialled for efficacy against multiple cancer types with a particular focus on B cell lineage malignancies such as B cell lymphomas." (PMID 35831623, 2022). "While EZH2 deletion suppresses the germinal center formation, in B-cell lymphomas, EZH2 gain-of-function in the SET domain, including changes in tyrosine 641, A677G or A687V, promotes alterations in the substrate-binding pocket, enhancing H3K27me3 and decreasing H3K27me2." (PMID 36135315, 2022). "More specifically, a gain-of-function mutant of EZH2 (Y641F), which is also found among B-cell lymphoma patients, acted in concert with wild-type EZH2 to elevate activating H3K27 trimethylation marks in Eμ-Myc transgenic mice, resulting in enforced B-cell receptor signaling and lethality." (PMID 36611833, 2022). "Results of a phase 1 trial have shown promising antitumor activity of tazemetostat in patients with refractory B-cell non-Hodgkin lymphoma (both EZH2 mutated and non-mutated)." (PMID 34945856, 2021). "Intriguingly, RNA sequencing also revealed enhanced expression of Prdm1, a master regulator of plasma cell proliferation and differentiation, which was found to be essential for the survival of WM cells by regulating EZH2, a promising therapeutic target in B-cell lymphoma." (PMID 34363012, 2021). "Although AHCY alterations are rare in primary B-cell lymphomas, it may still be important to screen for modifications of this gene in patients prior to the initiation of EZH2 based therapy with DZNep." (PMID 32408898, 2020). "Among these inhibitors, EPZ-6438 (Tazemetostat) is a representative that has already entered clinical trial phase I/II for the treatment of multiple malignancies with EZH2 aberrance, including GC-derived and other types of B cell lymphoma (NCT03010982, NCT03028103, NCT01897571, and NCT02875548)." (PMID 31752930, 2019).